SNHG1 (small nucleolar RNA host gene 1)
Diseases named in the same sentence as SNHG1 in open-access papers (continued):
Sharing a sentence is not in itself a finding about the gene and the disease.
prostate carcinoma (continued). "Then, targeting activities SNHG1 is involved in could play a role in prostate cancer treatment, and the biology of tumor dormancy and recurrence." (PMID 37464317, 2023). "In prostate cancer cell lines, SNHG1 silencing inhibited DNA synthesis and arrested cells in G0." (PMID 37464317, 2023). "In addition, SNHG1 can enhance proliferation and survival of prostate cancer cells via AKT2 upregulation." (PMID 35317831, 2022). "About promoting prostate cancer progression, SNHG1 can affect autophagy." (PMID 35317831, 2022). "we divided the sample into high (++, +++) and low (−, +) SNHG1 expression group according to the positive cell nuclear stain percentage of SNHG1 and then explored the correlation between the clinicopathological characters of prostate cancer patients and SNHG1 expressions." (PMID 33542227, 2021). "Finally, our previous work confirmed that SNHG1 triggers EMT pathway through directly binding to hnRNPL in the development of prostate cancer." (PMID 33542227, 2021). "The proliferation of prostate cancer cells could be enhanced by the lncRNA SNHG1 (Small Nucleolar RNA Host Gene 1) through its sponging with miR-199a-3p as a competing endogenous RNA20." (PMID 33589600, 2021). "As shown in, we identified SNHG1 transcript level is overexpression in prostate cancer." (PMID 33542227, 2021). "Metaherin, another oncogene implicated in metastasis in NSCLC, was upregulated by small nucleolar RNA host gene 1 (SNHG1) and prostate cancer non-coding RNA 1 [PRNCR1] by sponging miR-145-4p and miR-126-5p, respectively, increasing EMT, migration, and invasion of NSCLC cells." (PMID 32629922, 2020). "SNHG1 via regulating miR-199a-3p/CDK7 axis could promote cell proliferation in prostate cancer." (PMID 33330110, 2020). "Moreover, lncRNA SNHG1 negatively regulates miR-199a-3p to enhance CDK7 expression and promote cell proliferation in prostate cancer and can serve as diagnostic and prognostic markers for prostate cancer through androgen-responsive manner." (PMID 29340086, 2017). "SNHG1 is reported to bind to certain RBPs like heterogeneous nuclear ribonucleoprotein L (HNRNPL) and matrin 3 (MATR3) and to promote the progression of prostate cancer (PCa) as well as neuroblastoma." (PMID 40510136, 2025). "In prostate cancer cells, SNHG1 competitively inhibits miR-377-3p expression, leading to AKT2 hyperactivation, which facilitates proliferation and suppresses apoptosis in prostate cancer cells." (PMID 38706912, 2024). "For instances, small nucleolar RNA host gene 1 (SNHG1) promotes cell proliferation, migration, and invasion in cervical cancer; Pvt1 oncogene (PVT1) predicts the prognosis of prostate cancer and regulates tumor growth." (PMID 35266446, 2022). "In this way, SNHG1 induces PI3K-AKT signaling to induce MTOR expression, resulting in autophagy inhibition, paving the way for survival and proliferation of prostate cancer cells." (PMID 35317831, 2022). "The lncRNA small nucleolar RNA host gene 1 (SNHG1) is reported to increase cell proliferation, migration, and invasion in different cancers, including HCC, cervical cancer, prostate cancer, and non-small cell lung cancer." (PMID 34771549, 2021). "SNHG1 can activate the EMT (Epithelial Mesenchymal Transformation) pathway to promote the malignant progression of prostate cancer and is expected to be a therapeutic target for prostate cancer." (PMID 38605206, 2024). "LncRNA Small Nucleolar RNA Host Gene 1 (SNHG1) activates Wnt/β-catenin and PI3K/Akt/mTOR signaling pathways by targeting EZH2 (Enhancer of zeste homolog 2), and promoting proliferation, apoptosis and autophagy of prostate cancer (PCa) cells." (PMID 35309939, 2022). "Meng XF and others proved SNHG1 could mediate the proliferation, invasion, and EMT of prostate cancer by regulating miR-195-5p expression." (PMID 35310912, 2022).
prostate carcinoma (continued). "In addition to this, lncRNA SNHG1 and RNA binding protein hnRNPL were found to form a complex and coregulate CDH1 to enhance prostate cancer growth and metastasis." (PMID 35846429, 2022). "Furthermore, the SNHG1/hnRNPL complex lead to a downstream of E-cadherin via binding to its mRNA, which promotes EMT in prostate cancer." (PMID 33542227, 2021). "TCGA database analysis showed that SNHG1 and EZH2 were highly expressed in prostate cancer tissue." (PMID 33194612, 2020). "A previous report showed that lncRNA SNHG1 serves as a ceRNA to negatively regulate miR-199a-3p and enhance CDK7 expression, which might be a potential therapeutic target for prostate cancer." (PMID 31269941, 2019).
glioma (25 papers, 2017 to 2025). A benign or malignant brain and spinal cord tumor that arises from glial cells (astrocytes, oligodendrocytes, ependymal cells). "Evidence on malignant brain tumour tissues has demonstrated the enhanced expression of SNHG1 and is thus associated with malignant progression and unfavourable prognosis of glioma." (PMID 40928594, 2025). "The underlying molecular mechanism involves SNHG1 regulating the malignant behavior of glioma cells by interacting with microRNA-154-5p or miR-376b-3p." (PMID 38920691, 2024). "Taken together, these findings indicate that SNHG1 is upregulated in glioma and is associated with the grade of glioma." (PMID 31189920, 2019). "The underlying mechanisms of SNHG1 in glioma were also investigated using immunohistochemistry staining, Western blotting, chromatin immunoprecipitation, and RNA pulldown." (PMID 30728054, 2019). "There are also studies showed that SNHG1 promotes the progression of glioma, however, the underlying mechanism require further studied." (PMID 31189920, 2019). "We found that MS2-tagged wild-type SNHG1 (SNHG1-WT-MS2) was significantly enriched for miR-194 in glioma cells compared to the empty vector and SNHG1 with a mutation in the miR-194 binding site (SNHG1-MUT-MS2)." (PMID 31189920, 2019). "We aimed to determine whether SNHG1 was associated with glucose metabolism in glioma cell lines." (PMID 31189920, 2019). "Therefore, it is meaningful to explore the underlying molecular mechanism of SNHG1 in glioma." (PMID 31189920, 2019). "This study highlights the significance of the SNHG1-microRNA-154-5p/miR-376b-3p-FOXP2-KDM5B feedback loop in regulating the malignant behavior of glioma cells." (PMID 38920691, 2024). "In the present study, we investigated the altered lncRNAs upon ER stress in glioma and found that small nucleolar RNA host gene 1 (SNHG1) was markedly increased in response to ER stress." (PMID 37243389, 2023). "By regulating miR-154-5p and miR-376b-3p, SNHG1 induces malignant biological characteristics in glioma cells." (PMID 35676651, 2022). "For instance, SNHG1 functioned as an oncogene in glioma through increasing cell proliferation and invasion, and repressing apoptosis." (PMID 31907031, 2020). "SNHG1 aggravates malignancy of glioma cells through functioning as a sponge of miR-154-5p/miR-376b-3p to up-regulate FOXP2." (PMID 32536864, 2020). "In vitro and in vivo assays suggested that SNHG1 promoted glioma progression by functioning as a sponge for miR-194 and then inducing the high expression of pleckstrin homology like domain family A, member 1 (PHLDA1)." (PMID 32802843, 2020). "Functional studies demonstrated that knockdown of SNHG1 suppressed glioma cell proliferation and cell invasion and increased cell apoptosis." (PMID 32802843, 2020). "Next, we detected the expression of SNHG1 in glioma cell lines (A172, LN229, T98G, U87 and U251) and normal human astrocytes (NHAs)." (PMID 31189920, 2019). "Taken together, these results suggest that SNHG1 promotes the progression of glioma both in vitro and in vivo." (PMID 31189920, 2019). "To explore the function of SNHG1 in glioma, we transfected glioma cell lines with an shRNA targeting SNHG1 (sh-SNHG1-1 and sh-SNHG1-2), and the transfection efficiency was verified by qRT-PCR." (PMID 31189920, 2019). "According to the TCGA database, we identified SNHG1, miRNA-154-5p and miR-376b-3p whose expression were significantly changed in the glioma samples." (PMID 30728054, 2019). "In a recent glioma study, it has also been discovered that the expression of SNHG1 can reduce the proliferation and invasion of glioma cells, resulting in more cell apoptosis." (PMID 30728054, 2019). "This study confirms that SNHG1 interacts with miR-376b-3p, which is edited by A to I, and plays a sponge regulating effect of the miRNAs molecule, suggesting that SNHG1 and miR-376b-3p can produce stable effects in glioma cells." (PMID 30728054, 2019).
glioma (continued). "KDM5B exerts the effect of RNA binding protein, acts on SNHG1 to form a positive feedback loop, and regulates the biological behavior of glioma cells." (PMID 30728054, 2019). "SNHG1-miR-154-5p/miR-376b-3p-FOXP2-KDM5B feedback loop plays an important role in regulating the biological behavior of glioma cells." (PMID 30728054, 2019). "Silencing the expression of KDM5B in cell experiments significantly reduced the expression of SNHG1 in glioma cells." (PMID 30728054, 2019). "We also demonstrated that SNHG1 promotes glucose uptake and the proliferation, migration, invasion and angiogenesis of glioma in vitro and tumour growth in vivo." (PMID 31189920, 2019). "Collectively, this study demonstrates that the SNHG1- microRNA-154-5p/miR-376b-3p- FOXP2- KDM5B feedback loop plays a pivotal role in regulating the malignant behavior of glioma cells." (PMID 30728054, 2019). "Next, through online databases, a luciferase reporter assay and an RNA pull-down assay, we confirmed that SNHG1 functions as a sponge for miR-194, which acts as a suppressor in glioma." (PMID 31189920, 2019). "The qRT-PCR results showed that the expression of SNHG1 in glioma tissues was higher than that in normal brain tissues, and the expression level was positively correlated with the pathological grade of glioma (P < 0.01)." (PMID 30728054, 2019). "In the present study, we found that the expression of SNHG1 is upregulated in both glioma tissues and cell lines." (PMID 31189920, 2019). "Analysis of the differential expression of lncRNAs in TCGA showed that, compared to normal brain tissues, SNHG1 is markedly overexpressed in glioma tissues." (PMID 31189920, 2019). "According to the TCGA database, the expression of SNHG1 increased significantly in glioma samples in comparison with the normal brain tissue (P < 0.01)." (PMID 30728054, 2019). "A series of functional assays suggested that SNHG1 promotes glioma progression in vitro and in vivo." (PMID 31189920, 2019). "In order to clarify the biological role of SNHG1 in glioma cells, SNHG1 was stably silenced in malignant glioma cells U87 and U251, and the proliferation ability of the cells was detected by CCK-8 assay after confirming the transfection efficiency by qRT-PCR." (PMID 30728054, 2019). "Overall, these results suggest that SNHG1 promotes glioma progression by sponging miR-194 and regulating PHLDA1 expression." (PMID 31189920, 2019). "TTN-AS1 and SNHG1 are lncRNAs that promote glioma development by upregulating RUNX1." (PMID 35676651, 2022). "Also, SNHG1 contributed to glioma progression via competitively binding to miR-194 to modulate PHLDA1 expression." (PMID 31907031, 2020). "However, the upstream modulators of SNHG1 and the networks of downstream signalling that bestow the malignant phenotype on glioma cells remain undetermined." (PMID 31189920, 2019). "Functional assays revealed that SNHG1 promotes glioma progression via miR-194 to regulate PHLDA1." (PMID 31189920, 2019). "In this study, we clarified the mechanism of SNHG1 in the progression of glioma." (PMID 31189920, 2019). "Inspired by the competing endogenous RNA (ceRNA) mechanism, we speculated whether SNHG1 binds to miRNAs to regulate glioma progression." (PMID 31189920, 2019). "The expression of SNHG1 in malignant glioma cell lines U87 and U251 is higher than that in HA cells (P < 0.01), suggesting that SNHG1 may play a role in promoting the biological behavior of malignant tumor cells in glioma cells." (PMID 30728054, 2019). "In this study, we show that SNHG1 is overexpressed in glioma tissues and cell lines." (PMID 31189920, 2019). "In this study, we confirmed the overexpression of SNHG1 in glioma tissues and cell lines." (PMID 31189920, 2019). "Inspired by these studies, we hypothesized that SNHG1 regulates glioma progression via a ceRNA mechanism." (PMID 31189920, 2019).
glioma (continued). "To elucidate the ceRNA mechanism of SNHG1 in glioma, we conducted a series of experiments to explore whether SNHG1 regulates the expression of PHLDA1 in a miR-194-dependent manner." (PMID 31189920, 2019). "Compared to normal brain tissues, SNHG1 expression was higher in glioma tissues (P < 0.0001)." (PMID 31189920, 2019). "This analysis illustrated that SNHG1 acts as a tumor promoting factor in glioma tissues and cells." (PMID 30728054, 2019). "In conclusion, our study reports, for the first time, that SNHG1/miR-194/PHLDA1 signalling is involved in the progression of glioma, which leads to a more malignant phenotype and may be a novel potential therapeutic target for glioma." (PMID 31189920, 2019). "Through a literature search, we found that SNHG1 could bound to miR-154-5p/miR-376b-3p and attenuate its expression, thereby regulating glioma progression." (PMID 31189920, 2019). "The expression level of SNHG1 is correlated with the grade of glioma." (PMID 31189920, 2019). "Based on these findings, we wondered whether SNHG1 can adsorb other miRNAs to regulate the progression of glioma." (PMID 31189920, 2019). "In summary, our study shows that SNHG1 is overexpressed in glioma." (PMID 31189920, 2019). "SNHG1 was overexpressed in glioma cell lines, especially in U251 and U87." (PMID 31189920, 2019). "In previous studies, SNHG1 has been confirmed to be related to angiogenesis, and up-regulation of SNHG1 could promote the increase of angiogenesis in brain microvascular endothelial cells and glioma cells, implying SNHG1 was might be a modulator of angiogenesis." (PMID 34732133, 2021). "Similarly, overexpressed lncRNA SNHG1 promotes glioma progression in vitro and in vivo." (PMID 33652661, 2021). "Hence, the SNHG1/miR-194/PHLDA1 signalling pathway may be a potential therapeutic target for glioma." (PMID 31189920, 2019). "Studies on various malignant brain tumor tissues have revealed elevated expression levels of small nucleolar RNA host gene 1 (SNHG1), which correlates with the malignant progression and unfavorable prognosis of glioma." (PMID 38920691, 2024). "Small nucleolar RNA host gene 1 (SNHG1) is involved in several human cancers’ regulation, such as CRC, HCC, lung, prostate and oesophageal cancers, glioma and NB." (PMID 33921816, 2021). "Previous studies revealed the upregulation of ENST00000545920, also known as lnc-SNHG1, in CRC, non-small-cell lung cancer, gastric cancer, and glioma to promote cancer cell growth by interacting with EZH2 in the nucleus and miR-154-5p in the cytoplasm." (PMID 34211553, 2021). "SNHG1 regulates pleckstrin homology like domain family A member 1 (PHLDA1) expression by sponging miR-194, leading to an increased glioma cell glucose uptake, proliferation, migration, invasion, angiogenesis and in vivo tumor growth." (PMID 33652661, 2021). "SNHG1 competitively binds to miR-194 to relieve the inhibitory effect of miR-194 on PHLDA1 expression, thus promoting glioma progression." (PMID 32536864, 2020). "The present study suggests that SNHG1 acts as a sponge for miR-194 and that miR-194 targets PHLDA1 to regulate glioma progression." (PMID 31189920, 2019). "In this study, we intially identified the endogenous expression of SNHG1, miR-154-5p, miR-376b-3p, FOXP2, and KDM5B in gliomas." (PMID 30728054, 2019). "For instance, in glioma and HCC, miR-195-5p is sponged by LINC00473 and lncRNA SNHG1, respectively." (PMID 34346845, 2021). "Taken together, our study shows that SNHG1 promotes glioma progression by competitively binding to miR-194 to regulate PHLDA1 expression, which may provide a novel therapeutic strategy for glioma." (PMID 31189920, 2019). "In summary, this study demonstrates that SNHG1 increases the expression of FOXP2 and KDM5B by regulating the expression of miR-154-5p and miR-376b-3p, and that KDM5B itself and its downstream PI3K/Akt pathway affect the biological behavior of glioma cells." (PMID 30728054, 2019).
glioma (continued). "However, it is important to highlight that SNHG1 is not the only factor secreted by glioma CSCs, and therefore, more studies are required to identify all the potential agents involved in glioma progression in order to target appropriate molecules." (PMID 34638913, 2021). "To address our hypothesis, we performed glucose uptake assays and found that SNHG1 downregulation suppressed glucose uptake in glioma cells and attenuated the expression of genes involved in glucose metabolism, including HK2 and GLUT1 (, whereas the upregulation of SNHG1 showed the opposite results." (PMID 31189920, 2019). "Moreover, further analysis revealed that SNHG1 regulates pleckstrin homology like domain family A, member 1 (PHLDA1) expression via the sponging miR-194, leading to the subsequent promotion of glioma cell glucose uptake, proliferation, migration, invasion, angiogenesis and in vivo tumour growth." (PMID 31189920, 2019).